FGF18 (fibroblast growth factor 18)
Diseases named in the same sentence as FGF18 in open-access papers (continued):
Sharing a sentence is not in itself a finding about the gene and the disease.
cancer (continued). "FGF18 is a class of bioactive substances that can conduct biological signals, regulate cell growth, participate in tissue repair and other functions, and can promote the occurrence and development of different types of malignant tumors through various mechanisms." (PMID 37228502, 2023). "On the other hand, the upregulated genes, such as GNG12, GNG4, WNT9A, EDNRB, FGF18, LAMA3, MMP2, etc., were found in pathways in cancer." (PMID 36239109, 2022). "Surprisingly, FGF18 were expressed significantly lower in the cancer tissue of KIRC, LUAD, BLCA, and PRAD compared to normal tissues, while FGF18 were significantly up-regulated in the cancer tissue of COAD, LIHC, and STAD, compared to normal tissues." (PMID 33117668, 2020). "Among these target genes, KLK9, WNT3A, FGF18, FIBP, SOX12, TGFBI, and NEDD9 have been reported to participate in the development of human cancers." (PMID 33344223, 2020). "Enriched genes also included factors involved in cancer pathways and PI3K/AKT signalling, including IRS1, BCL2, TGFB3 and FGF18." (PMID 26698305, 2015). "Although the roles of FGF18 and CDK10 in cell cycle progression and proliferation have been well studied, the relationship between their copy number and cancer survival is not fully understood." (PMID 26683928, 2015). "Increased expression of FGF18 and OPN has been observed in fibrotic livers and various cancers." (PMID 40678531, 2025). "FGF8, FGF18, and FGFR4 have been identified as promising biomarkers in a number of cancers; however no data exist on expression of FGF8, FGF18, and FGFR4 in adenocarcinomas of the esophago-gastric junction (AEG)." (PMID 31527546, 2019).
infection (2 papers, 2022 to 2023). The state of being infected such as from the introduction of a foreign agent such as serum, vaccine, antigenic substance or organism. "Additionally, overexpression of FGF18 by lentiviral infection or direct addition of FGF18 to culture media induced the expression of osteoblast marker genes in C3H10T1/2 fibroblastic cells." (PMID 36759827, 2023). "To further confirm the involvement of FGF18 in HDAC7-regulated NSCLC progression, we upregulated FGF18 in A549 HDAC7 knockdown cells and downregulated FGF18 in SK-LU-1 HDAC7 overexpressing cells using lentivirus infection." (PMID 35277183, 2022).
adenocarcinoma (1 paper, 2019). A common cancer characterized by the presence of malignant glandular cells. "In contrast to these results, our data show a significantly improved OS in neoadjuvantly treated patients with adenocarcinomas of the esophago-gastric junction when the tumors are high in FGF18." (PMID 31527546, 2019). "Until now, no data exists on the expression of FGF8, FGF18, and FGFR4 on adenocarcinomas of the esophago-gastric junction investigated by immunohistochemistry and no signifier scoring method is available." (PMID 31527546, 2019).
liver (1 paper, 2023). "Notably, FGF18 counteracts TGFβ-mediated YAP dephosphorylation, facilitating the degradation of phosphorylated YAP and preventing liver fibrosis." (PMID 37813881, 2023).
FGF18 also shares sentences with these, for which no sentence is quoted: alopecia (2 papers); fibrosis (2); liver disease (2); metabolic syndrome (2); atherosclerosis (1); benign ovarian tumors (1); cardiovascular diseases (1); cholangiocarcinoma (1); chondrosarcoma (1); COVID-19 (1); diabetic cardiomyopathy (1); dwarfism (1); gastric ulcer (1); glioblastoma (1); hemarthrosis (1); Hyperglycemia (1); ischemia (1); large cell lung carcinoma (1); leukaemia (1); liposarcoma (1); mesothelioma (1); nasopharyngeal carcinoma (1); ovarian tumor (1); Peptic ulcer (1); prostate carcinoma (1); renal carcinoma (1); sarcoma (1); skeletal disease (1); skeletal dysplasia (1); trauma (1).